NAP1L5 (nucleosome assembly protein 1 like 5)
Synonyms: DRLM
Tractability: PROTAC: ubiquitination databases record sites on it; its protein half-life has been measured.
Gene: Protein-coding gene on chromosome 4 (88,695,913 to 88,697,829, reverse strand). Ensembl gene ENSG00000177432.
Subcellular location: Nucleus
Subcellular location (Human Protein Atlas): Nucleoplasm; Cytosol
Gene Ontology:
Molecular function: protein binding
Biological process: nucleosome assembly
Cellular component: nucleus
Genetic constraint (gnomAD): Loss-of-function variants: 0 observed, 0.15 expected, observed/expected ratio (o/e) 0, 90% interval 0 to 1.88. That is too few expected variants to judge how well the gene tolerates losing a copy. Missense variants: 249 observed, 250.36 expected, observed/expected ratio (o/e) 0.99, 90% interval 0.9 to 1.11. Synonymous variants: 125 observed, 108.44 expected, observed/expected ratio (o/e) 1.15, 90% interval 1 to 1.34.
Homologues: Orthologues: macaque NAP1L5 (99% identical), dog NAP1L5 (83% identical), chimpanzee NAP1L5 (79% identical), mouse Nap1l5 (68% identical), rat Nap1l5 (66% identical), rabbit NAP1L5 (60% identical), zebrafish nap1l4a (24% identical), zebrafish tspy (22% identical), Drosophila melanogaster Set (21% identical), Caenorhabditis elegans spr-2 (20% identical), Drosophila melanogaster Nap1 (19% identical), Caenorhabditis elegans nap-1 (16% identical), and 2 more. Paralogues in human: NAP1L1 (32% identical), NAP1L4 (28% identical), NAP1L2 (27% identical), SETSIP (25% identical), TSPYL2 (23% identical), SET (23% identical), TSPYL1 (20% identical), NAP1L3 (18% identical), TSPYL4 (16% identical), TSPYL6 (15% identical), TSPYL5 (14% identical), TSPY1 (13% identical), and 6 more.
Diseases named in the same sentence as NAP1L5 in open-access papers:
NAP1L5 is named in the same sentence as 18 diseases in open-access papers, as found by Europe PMC text mining. Sharing a sentence is not in itself a finding about the gene and the disease. The quoted sentences say what the papers report.
hepatocellular carcinoma (2 papers, 2022 to 2023). A malignant tumor that arises from hepatocytes. "NAP1L5 inhibits the malignant biological characteristics of hepatocellular carcinoma cells in vivo and in vitro." (PMID 36374212, 2022). "In this study, we first proved the downregulation of NAP1L5 in hepatocellular carcinoma tissue and that the downregulation of NAP1L5 is related to shorter overall and disease-free survival times." (PMID 36374212, 2022). "In this study, low expression of NAP1L5 was found in hepatocellular carcinoma, and the downregulation of NAP1L5 was related to shorter survival and disease-free survival." (PMID 36374212, 2022). "In the mechanistic study, we found that NAP1L5 affects the occurrence and development of hepatocellular carcinoma by regulating MYH9 to inhibit the PI3K/AKT/mTOR signaling pathway." (PMID 36374212, 2022). "We searched the TCGA database for the RNA expression of NAP1L5 in hepatocellular carcinoma and found that the expression of NAP1L5 in cancer tissues was lower than that in adjacent tissues." (PMID 36374212, 2022). "In vivo experiments confirmed that NAP1L5 can inhibit the growth and metastasis of hepatocellular carcinoma cells." (PMID 36374212, 2022). "The overexpression and knockdown of NAP1L5 by plasmid and siRNA showed that NAP1L5 inhibited the proliferation, migration and invasion and induced apoptosis of hepatoma cells." (PMID 36374212, 2022). "The results showed that the expression of NAP1L5 was downregulated in hepatocellular carcinoma." (PMID 36374212, 2022). "NAP1L5 inhibits the PI3K/AKT/mTOR signaling pathway in hepatocellular carcinoma by regulating MYH9." (PMID 36374212, 2022). "However, the role of NAP1L5 in the pathogenesis of hepatocellular carcinoma remains to be elucidated." (PMID 36374212, 2022). "Through the discussion of the clinicopathological features of the patients, it was found that the expression of NAP1L5 was related to tumor volume, survival time and recurrence (P < 0.05), suggesting that NAP1L5 may have antitumor activity in hepatocellular carcinoma." (PMID 36374212, 2022). "In addition, we found that NAP1L5 may inhibit the progression of hepatocellular carcinoma by inhibiting the PI3K/AKT/MTOR signaling pathway." (PMID 36374212, 2022). "NAP1L5 inhibits tumor growth and metastasis by inhibiting the PI3K/Akt/mTOR signaling pathway and myosin heavy chain 9 in hepatocellular carcinoma." (PMID 37667226, 2023). "We proved the interaction between NAP1L5 and MYH9 by mass spectrometry and Co-IP and found that they regulated the downstream signaling pathways and functions of hepatocellular carcinoma cells." (PMID 36374212, 2022). "We found that the mRNA and protein expression levels of NAP1L5 in hepatocellular carcinoma cell lines were lower than those in noncancer cell lines." (PMID 36374212, 2022). "To date, the role and mechanism of human NAP1L5 in the progression of hepatocellular carcinoma are not clear." (PMID 36374212, 2022). "We used RT–qPCR and Western blotting to study the expression of NAP1L5 in hepatocellular carcinoma cell lines and noncancerous liver cell lines." (PMID 36374212, 2022).
cardiac hypertrophy (1 paper, 2021). "Our data provide crucial evidence that overexpression of Nap1l5 aggravates cardiac hypertrophy along with increased ribosome assembly and translation activity." (PMID 34977198, 2021). "Our findings demonstrate a previously unrecognized role of Nap1l5 in translation control during cardiac hypertrophy." (PMID 34977198, 2021). "Our findings demonstrate a novel role of NAP1L5 in translation control during the pathological growth of cardiomyocytes, and provide potential molecular targets to treat cardiac hypertrophy." (PMID 34977198, 2021). "Whether and how NAP1L5 links to the ribosome assembly process and contributes to the pathogenesis of cardiac hypertrophy need to be further investigated." (PMID 34977198, 2021).
congenital heart disease (1 paper, 2022). A heart disease that is present at birth. "As one of the members of the NAP1L protein family, NAP1L5 was identified as an imprinted gene in human liver malignancy and congenital heart diseases and an important regulator of translation activation during cardiomyocyte hypertrophy." (PMID 36568274, 2022). "NAP1L5, first identified in the human liver malignancy as an imprinted gene, was also found to be hypomethylated in congenital heart diseases." (PMID 36568274, 2022).
gestational diabetes mellitus (1 paper, 2018). "NAP1L5, for example, has been previously identified to be differently methylated in cord blood samples characterized by intrauterine exposure to gestational diabetes mellitus." (PMID 29930742, 2018).
gout (1 paper, 2019). A condition characterized by painful swelling of the joints, which is caused by deposition of urate crystals. "We identified three genes, which were significantly associated with the risk of gout (PKD2, NUTD9, and NAP1L5), with NUTD9, and NAP1L5 reported at the first time." (PMID 30899057, 2019). "One eSNP (rs4148155) showed significant association with both PKD2 (LBFG = 7.02, PeQTL = 2.00 × 10−5) and NAP1L5 expression (LBF = 5.62, PeQTL = 2.00 × 10−4) and strong evidence for association with gout (PGWAS = 5.49 × 10−18)." (PMID 30899057, 2019). "Through systematic integration of lymphoblastoid eQTL and SNP associations from our discovery GWAS analysis, PKD2 expression showed the most significant association with gout (LBF = 6.89, Psher = 1.08 × 10−5) followed by NUTD9, NAP1L5, and BRE." (PMID 30899057, 2019). "Sherlcok analysis identified three genes, which were significantly associated with the risk of gout (PKD2, NUTD9, and NAP1L5)." (PMID 30899057, 2019). "Currently, the biological mechanism on how ABCG2 interacts with PKD2/NAP1L5 in the pathogen of gout is unclear." (PMID 30899057, 2019). "To conclude, the results of our study may contribute to the understanding of the genetic causes of gout, and future studies are needed to confirm and explore the role of NUTD9, and NAP1L5 in the pathogenesis of gout." (PMID 30899057, 2019). "In addition, we conducted Sherlock analysis to identify susceptibility genes in with regulatory function in gout, and identify three genes, which were significantly associated with the risk of gout (PKD2, NUTD9, and NAP1L5)." (PMID 30899057, 2019).
hypertrophic cardiomyopathy (1 paper, 2021). A condition in which the myocardium is hypertrophied without an obvious cause. "Gene set enrichment analysis (GSEA) also showed that hypertrophic cardiomyopathy-related genes were enriched in the down-regulated genes after NAP1L5 knockdown, suggesting an involvement of NAP1L5 in hypertrophic cardiomyopathy." (PMID 34977198, 2021).
liver cancer (1 paper, 2022). An epithelial or non-epithelial malignant neoplasm that arises from the liver. "This suggests that NAP1L5 may be a new biomarker with which to evaluate the prognosis of liver cancer and a potential therapeutic target for liver cancer." (PMID 36374212, 2022). "Our findings suggest that NAP1L5 may become a potential biomarker for liver cancer diagnosis and a new target for treatment in the future." (PMID 36374212, 2022). "To explore the effect of NAP1L5 in HCC, we first detected the expression of NAP1L5 in liver cancer clinical tissue specimens and the public TCGA database." (PMID 36374212, 2022). "Through mass spectrometry analysis and GO enrichment analysis, we found that the overexpression of NAP1L5 was highly related to the PI3K/AKT/MTOR signaling pathway and proved that NAP1L5 inhibited the progression of liver cancer through the PI3K/AKT/MTOR signaling pathway." (PMID 36374212, 2022).
tauopathies (1 paper, 2022). "In the current study, we observed that NAP1L5 overexpression markedly reduced phospho-Tau Ser396 and Thr231 in N2a-APP695sw cells, indicating that NAP1L5 overexpression could alleviate the tauopathies of AD." (PMID 36568274, 2022).
tumor (6 papers, 2013 to 2025). "To explore the potential role of NAP1L5 in AML immunotherapy, we investigated its association with tumor immune dysfunction and exclusion (TIDE) scores and tumor mutational burden (TMB)." (PMID 40786510, 2025). "As an oncogene, NAP1L5 is involved in cell division, cellular aging, and tumorigenesis, promoting tumor cell survival, proliferation, colony formation, and invasion." (PMID 40786510, 2025). "Nucleosome assembly protein 1-like 5 (NAP1L5) is a histone chaperone that acts as a tumor suppressor." (PMID 39273383, 2024). "As a functional tumor suppressor, NAP1L5 is expressed at low levels in HCC." (PMID 36374212, 2022). "The expression of NAP1L5 and MEST in the tumor regions was decreased, for which the methylation of the originally unmethylated allele was responsible." (PMID 41187747, 2025). "In HCC, NAP1L5 downregulates MYH9 which, in turn, inhibits PI3K/AKT/mTOR signaling, leading to its tumor-suppressive effects." (PMID 39273383, 2024). "The following DMRs showed aberrant methylation in only one tumor: ARH1-CG1, NAP1L5-DMR, PEG10-DMR, H19 promoter, WT1-AS-DMR, MEG3-CG7-DMR, MCTS2-DMR, NESP-DMR, and GNAS1A-DMR." (PMID 24373183, 2013). "Notably, high NAP1L5 expression correlated with increased infiltration of resting CD4+ memory T cells, implicating its potential influence on the tumor immune microenvironment." (PMID 40786510, 2025). "NAP1L5 and SESN1 have been shown to act as tumor suppressors in previous studies on cancer." (PMID 37667226, 2023).
cancer (4 papers, 2015 to 2025). A tumor composed of atypical neoplastic, often pleomorphic cells that invade other tissues. "Nucleosome assembly protein 1-like 5 (NAP1L5), a critical regulator of gene transcription and nucleosome assembly, has been implicated in the progression and poor prognosis of various cancers." (PMID 40786510, 2025). "Dysregulated NAP1L5 expression has been implicated in various cancers." (PMID 40786510, 2025). "The protein content of NAP1L5 in cancer tissue was lower than that in adjacent tissue." (PMID 36374212, 2022). "Thus, exploring NAP1L5 may provide insights into nucleosome assembly and DNA repair mechanisms, potentially offering novel therapeutic avenues for cancer treatment." (PMID 40786510, 2025).
neurodegenerative disease (2 papers, 2022 to 2025). A disorder of the central nervous system characterized by gradual and progressive loss of neural tissue and neurologic function. "In addition to Nap1l5, histone chaperone Nap1l2 regulates neuronal proliferation by interacting with chromatin while associated with AD among other neurodegenerative diseases." (PMID 40979532, 2025). "Among these genes of neurodegenerative diseases, we observed that the NAP1L5 expression was significantly positively correlated with NEUROD6 and NRN1, whereas correlated with negatively CD163, ITPKB, and AQP1." (PMID 36568274, 2022). "In addition, NAP1L5, upon the results form bioinformatics analysis, was strongly correlated with neurodegenerative diseases." (PMID 36568274, 2022).
infection (1 paper, 2021). The state of being infected such as from the introduction of a foreign agent such as serum, vaccine, antigenic substance or organism. "Both qRT-PCR and Western blot analyses confirmed the overexpression of NAP1L5 48h after infection." (PMID 34977198, 2021).
NAP1L5 also shares sentences with these, for which no sentence is quoted: acute myeloid leukemia (1 paper); Alzheimer disease (1); Obesity (1); ovarian carcinoma (1); pancreatic neuroendocrine neoplasm (1); Parkinson disease (1).